WT1 (WT1 transcription factor)
Diseases named in the same sentence as WT1 in open-access papers (continued):
Sharing a sentence is not in itself a finding about the gene and the disease.
tumor (continued). "Immunohistochemically, the tumor cells were diffusely positive for CAM5.2, AE1/AE3, and ER; focally positive for CD10, EMA, vimentin, WT1, CDX2, and p16; and negative for PAX8, CK7, calretinin, GATA3, Napsin A, and TTF1." (PMID 40959354, 2025). "Immunohistochemical studies confirmed the diagnosis, with tumor cells positive for pancytokeratin, TTF1, synaptophysin, and INSM1, and negative for Napsin-A, p40, WT1, calretinin, and chromogranin." (PMID 40403473, 2025). "The tumor was positive for synaptophysin, CK-AE1/3, focal CDX-2, and focal chromogranin, while Müllerian markers (PAX8, WT-1, ER, and PR) were negative, supporting a diagnosis of primary ovarian LCNEC." (PMID 41149460, 2025). "Tumor cells expressed Ki-67 at approximately 60%, while SATB2, H3.3G34 W, WT1,and p63 exhibited negative expression." (PMID 38903727, 2024). "Regarding WT1 immunoexpression cellularity in tumor-adjacent HRT, WT1-positive endothelial cells were rarely noted, in only 16.7% of TD HKTE(+) RCC samples and in none of the TD HKTE(−) RCCs." (PMID 38929778, 2024). "Additional amplification of WT1, ERC1, ASIC2 and MTCP1 and deletion of CDKN2A and MLLT3 were found in recurring MFS (case 8b) but not in the original tumor (case 8a)." (PMID 38791144, 2024). "Immunohistochemistry staining showed the tumour was positive for AE1/3, CK7, GATA-3 and GCDFP-15; and was negative for CK20, PAX-8, CDX-2, WT-1, TTF-1, mammaglobin and BRAF V600E." (PMID 36871042, 2023). "During the first round of immunohistochemical stains, the tumor cells showed positivity for CD56, CD99 (diffuse to patchy), INSM1, and NKX2.2, while they were negative for desmin, cytokeratin, SS18-SSX, and WT-1." (PMID 36765856, 2023). "Numerous blood vessels (less so in number and intensity the tumor cells) were marked by the immunohistochemistry for CD34 (asterisk) and Wilm’s tumor protein (WT1, not shown)." (PMID 36805296, 2023). "Tumor cells do not express EMA and CD10, while calretinin, inhibin, WT1, CD56, and SOX9 are diffusely and strongly expressed." (PMID 38136408, 2023). "The tumor cells were positive for AE1/AE2, calretinin, WT-1, D2-40, HEG1, EMA, BAP1, and MTAP and negative for carcinoembryonic antigen, MOC-31, Ber-Ep4, ER, PgR, TTF-1, claudin 4, and desmin." (PMID 36896044, 2023). "For non-immune cell populations, we identified tumor cells (EPCAM and CLDN4), fibroblasts (COL3A1 and NNMT), and mesothelial cells (LRRN4 and WT1)." (PMID 36788228, 2023). "At immunohistochemical examination, tumor cells stained negative for CK7, CD10 and RCC and positive for both WT1 (nuclear, intense) and vimentin (cytoplasmic, intense, and diffuse)." (PMID 35198098, 2022). "Core biopsy of left chest wall nodule also revealed poorly differentiated LUAD with tumor cells positive for pan-keratin and TTF-1 and negative for ER, PR, CDX2, WT1, PAX-8, synaptophysin and chromogranin." (PMID 35546239, 2022). "IHC studies show the tumor cells to be positive for FLI-1 and negative for S100 protein, SOX10, desmin, myogenin, WT1, SMA, CD34 and pan-cytokeratin." (PMID 34745213, 2021). "Tumor cells of case No. 2 were positive for AE1/AE3, CK7, calretinin, D2-40, focal positive for WT-1, and negative for HMB45, Melan-A, Desmin, S100, Syn, CgA, CD31, and CD34." (PMID 34248850, 2021).
tumor (continued). "The tumor cells in all 7 cases expressed IHC stains for PAX8, ER and CK7 and PR and were negative for CK20, CDX2 and WT1." (PMID 33736662, 2021). "All four MC-type HOV lines were negative for HNFB1 and WT1, and three out of four were negative for PAX8, while both HOV35 and its original tumor were positive for PAX8." (PMID 31248002, 2019). "Immunohistochemically (IHC) staining revealed that the tumor cells were diffusely positive for cytokeratin (CK) 5/6, p40, desmocollin 3, claudin 4, and MOC31, whereas they were negative for WT1, D2-40, S100 protein, GFAP, CD34, c-kit, NUT, and calponin." (PMID 29625594, 2018). "However, it is recognised that the stromal subtype of WT, common in children with WT1 mutant tumours, may not shrink and may even show a paradoxical increase in tumour size owing to rhabdomyoblastic differentiation, even though it is a favourable histological subtype." (PMID 28716159, 2017). "IVS confirmed the presence of polyfunctional CD4+ MAGE-specific T cells, as well as reactivity to other tumor antigens PRAME, survivin, HER2 and Wt1 (not seen or tested for in ex-vivo assays)." (PMID 28837000, 2014). "Immunostains showed the tumor cells to be diffusely positive for CK7 and negative for CK20, WT1, D240, calretinin, CK5/6 and TTF1." (PMID 22284391, 2012). "Only one tumor (GOS 219) showed CNAloss involving chromosome 11, which, in this case, did not involve the WT1 locus." (PMID 21544195, 2011). "Tumor cells were positive for cytokeratin (CK), cytokeratin 7 (CK7), estrogen receptor (ER) and progesterone receptor (PR), but negative for Wilms' tumor 1 (WT‐1)." (PMID 41152971, 2025). "Desmin, SMA, S100, CD31, Caldesmon, TLE-1, WT-1 and SS18 were negative in the tumor." (PMID 40831926, 2025). "Tumor cells of another case are negative for CD99, WT-1, S100, synaptophysin, and chromogranin." (PMID 38854270, 2024). "In the IHC study, tumor cells showed positivity for CD99, EMA, vimentin, and TLE1, while they were negative for NKX2.2, WT1, BCOR, PDGFA, cytokeratins, muscle markers (smooth muscle actin, desmin, caldesmon, MyoD1, and myogenin), and melanocytic markers (HMB45, SOX10, and S100)." (PMID 38339014, 2024). "Immunohistochemical analysis of tumor cells is positive for epithelial-derived markers such as CK, alveolar epithelial markers such as TTF-1, NapsinA, and CK7, and negative for mesothelial cell markers such as WT-1, calretinin, D2-40, and CK5/6." (PMID 37194050, 2023). "The tumor cells were negative for AE1/3, Cam5.2, CKIT, DOG1, CD99, SOX10, S100, HMB45, MelanA, Syn, CgA, Trypsin, Desmin, SMA, Caldesmon, collagen type 4, Laminin, Inhibin, Calretinin, STAT6, CD34, ERG, WT1, ER, PR, and SALL4." (PMID 36928336, 2023). "Immunohistochemical staining showed that the tumor cells were positive for thyroid transcription factor 1 (TTF-1) and CEA, but negative for prostate-specific antigen (PSA), Wilms tumor 1 (WT-1), p40, cytokeratin 5/6 (CK5/6), CK7, CK20 and anaplastic lymphoma kinase (ALK)." (PMID 38142271, 2023). "Indeed, tumor cells were positive for CD57 and WT1 and negative for P504S but also showed a partial positivity for CK7 and the immunohistochemical analysis for BRAF VE1 antibody was negative." (PMID 33175195, 2021). "Suppression of tumor growth, as assessed by tumor volume and visual observation of the surgically resected tumors at the end of the experiment, was seen with the WT1+ tumors but not with the WT1− tumors." (PMID 32259478, 2020).
tumor (continued). "Immunohistochemically, the tumor cells were positive for epithelial markers (AE1/AE3, EMA), a smooth muscle marker (desmin), and less specific sex-cord markers (CD56, WT-1, CD99), but negative for relatively specific sex-cord markers (α-inhibin, calretinin, FOXL2, and SF1)." (PMID 32921307, 2020). "Tumor cells were negative for gross cystic disease fluid protein (GCDFP-15), estrogen receptor, progesterone receptor, HER2, CDX-2, carcinoembryonic antigen (CEA), and Wilms Tumor 1 (WT1)." (PMID 31699107, 2019). "Additional experiments performed in Batf3−/− knockout mice deficient for both CD103+ and CD8α+ DCs29, 43 revealed an absence of the WT1 vaccine-mediated protective responses, stressing the need for CD103+ DCs at the tumor site for induction of antitumor protective immune responses." (PMID 31384667, 2019). "The tumor was negative for glial fibrillary acidic protein (GFAP), Wilms tumor 1 (WT1), myo-D1, myogenin, smooth muscle actin, nonphosphorylated and phosphorylated neurofilament protein, CD34, CD31, HMB-45, S-100, leukocyte common antigen, and BAF47/INI-1 (retained nuclear positivity)." (PMID 31372595, 2018). "Consistent with the reciprocal expression of WT1 and MUC-1, the remaining six blastemal-predominant tumours that all lacked WT1-negative epithelial structures were devoid of immuno-reactivity for MUC-1 in the examined sections, indicating the absence of UB-like structures." (PMID 29040332, 2017). "The tumor showed positive immunostaining for Vimentin, CD31, CK7, D2–40, c-MYC, Ki67, focal positivity for PanCK, and negative immunostaining for Factor VIII, CD34, WT1, CK5/6, Calretinin, EMA, HBME-1, CEA, p63, EpCAM, Bcl-2, TTF1 and Thyroglobulin." (PMID 28810922, 2017). "In this model, WT1 protein was not added to Poly(I:C), and WT1-specific CD8+ T cells was only subtly induced; the Poly(I:C)-induced increase in WT1-tetramer+ CD8+ T cells was below the detection limit in spleen and tumor tissue." (PMID 27619885, 2016). "Additionally, the tumor cells were negative for desmin, myogenin, leukocyte common antigen (LCA), CD20, CD3, cytokeratin, P63 and Wilms’ tumor 1 (WT-1)." (PMID 25435942, 2015). "The tumor cells are negative for CD3, CD20, CD30, alpha-fetoprotein, beta human chorionic gonadotrophin, pan-cytokeratin, CAM5.2, myogenin, epithelial membrane antigen, thyroid transcription factor-1, CK20, desmin, smooth muscle actin, HMB45, S100, and WT1." (PMID 22312368, 2012). "Thirty-one of these tumours were positive for WT1 expression by immunohistochemistry, a marker of serous cell type in EOC, thus confirming our histopathological subclassification; all clear cell and endometrioid cancers in this study were negative for WT1 expression (data not shown)." (PMID 18208621, 2008). "We and others have reported that TMS1, 14-3-3sigma and WT1 genes are methylated more frequently in clear cell tumours than in other tumour types, whereas methylation of SFRP1, 18S and 28S ribosomal DNA genes is more frequently detected in nonclear cell tumours, such as the serous type." (PMID 16479257, 2006). "The microcystic pattern can also be misleading with cystic/sieve-like areas of female adnexial tumor of Wolffian origin (FATWO), which could have similar immunohistochemical characteristics (no EMA or PAX8 expression, focal or negative ER/PR expression, and expression of CD10 and WT1)." (PMID 38136408, 2023). "In addition to the antigens described here, the original tumor was positive for CKC, CK7 and CK 5/6, negative for GATA3, CDX2, ERα, CK20,p63, AFP, CA19.9, TTF1 and PAX 8 and with patchy/focal staining for calretinin, CD10, RCC, BerEP4 and WT‐1 (data not shown)." (PMID 30109783, 2018).
cancer (411 papers, 1997 to 2026). A tumor composed of atypical neoplastic, often pleomorphic cells that invade other tissues. "The downregulation of the transcription factor Wilms' Tumor 1 (WT1) in cancer is associated with increased motility, invasiveness, and metastatic potential." (PMID 41899426, 2026). "The WT1 gene, situated on chromosome 11p13, encodes a zinc finger transcription factor that plays a vital role in both developmental processes and cancer biology." (PMID 40507300, 2025). "Conversely, loss-of-function mutations in WT1 have been reported in hematologic malignancies, suggesting a dual role in cancer pathogenesis." (PMID 40434298, 2025). "INO-5401 is an example of a synthetic DNA cancer vaccine encoding a variety of cancer antigens such as human telomerase reverse transcriptase (hTERT), WT1, and prostate-specific membrane antigen (PSMA)." (PMID 39789208, 2025). "While different levels of methylation have been correlated to distinct WT1 expression in several types of cancer, its hypomethylation is associated with more cytoplasmic expression in muscle cells." (PMID 39768169, 2024). "The Wilms Tumor-1 (WT1) protein is encoded by the WT1 gene and has been shown to have an oncogenic role in several cancers." (PMID 38611047, 2024). "Wilms’ tumor 1 (WT1) has been reported to be highly expressed in various cancers, functioning as an oncogene and associated with a poor prognosis." (PMID 38190392, 2024). "Previous studies in various cancer cell lines demonstrated that loss of WT1 results in decreased proliferation by interfering with antiapoptotic functions." (PMID 38190392, 2024). "Overexpression of WT1 is associated with these cancers, and targeted protein knockdown inhibits cancer growth." (PMID 38774284, 2024). "These vaccines elicit a targeted immune response against WT1-expressing cancer cells, potentially minimizing the risk of relapse and enhancing survival rates, with some patients achieving long-term remission." (PMID 39062028, 2024). "Cancer surveillance was performed in patients with WT1 gene mutations because malignancy remains a significant concern for the long-term outcomes of transplantation." (PMID 39363361, 2024). "Docking and dynamic simulations demonstrated the effectiveness of WA in encaging Hh proteins, curbing VEGF and modulating the PRKC apoptosis WT1 regulator protein, all of which are associated with cancer-suppression mechanistic pathways." (PMID 38446743, 2024). "Cancer vaccines have been explored in BTCs using WT1 and MUC1 as antigens due to their ubiquity: WT1 is mutated in ~80% of BTCs, while MUC1 is overexpressed in ~90%." (PMID 37444422, 2023). "Network analysis of WT1 coexpressed genes indicated that WT1 was coexpressed with genes functionally involved in cell motility or aggressiveness of cancer cells, again suggesting its association with the metastasis of NSCLC cells." (PMID 37667197, 2023). "For example, Wang and Wang have shown that WT1 preserves normal growth patterns in mammary epithelial cells, with downregulated expression associated with cancer development." (PMID 35915803, 2022). "Last, we looked at the possible cross-reactivity between the in-house established CMV-specific T cell line (HD-2) and T-cell clone (HD-2-A1-8, 9) with WT1 or survivin, a different unrelated cancer associated antigen." (PMID 36824620, 2022). "We encapsulated pancreatic cancer-associated antigen WT1 short peptide into the liposomes, and incubated them with CD14+ isolated monocytes." (PMID 34394090, 2021). "The fact that A3A induces particular changes in WT1 mRNA which correspond to driver cancer mutations suggests a potential role for this novel modification in cancer mutagenesis." (PMID 25807502, 2015).
cancer (continued). "In 2009, the cancer antigen prioritization project of the National Cancer Institute ranked Wilms tumor 1 (WT1) and mucin 1, cell-surface associated (MUC1) as the highest and second highest priority antigens, respectively." (PMID 25526950, 2014). "Combining WT1 IgG Ab levels and WT1 staining, patients with high-WT1 IgG Ab levels in plasma and positive WT1 protein staining in cancer tissues had shorter survival, with a significant association in PFS (P = 0.016)." (PMID 24715586, 2014). "Many recent studies have highlighted the potential of the WT1 protein as a tumor-associated antigen and a candidate for targeted cancer immunotherapy." (PMID 25026998, 2014). "The ability of Myc to regulate SRSF1 and of WT1 to regulate SRPK1 expression is particularly interesting as these two transcription factors are associated with a wide range of cancers." (PMID 24101931, 2013). "• Of the thirteen TFs found which co-regulate genes with WT1 (p ≤ 0.02), 8 have been previously implicated in cancer." (PMID 18564415, 2008). "A WT1 mRNA variant (706 bp) was expressed in 2 of 6 pT2 carcinoma samples, while the major WT1 mRNA was strongly expressed in pT3 and HR (N1 and/or M1) carcinoma samples." (PMID 17137506, 2006). "Indeed, this epigenetic effect was particularly pronounced for IL20RB and WT1 in the presence of BAP1 somatic cancer driver mutations (Fig. EV5)." (PMID 39592856, 2024). "Wilms’ tumor protein 1 (WT1) is a tumor-associated antigen (TAA) overexpressed in various cancers." (PMID 36853720, 2023). "All these predicted roles of WT1 coexpressed genes were tightly linked with the cell motility and aggressiveness of cancer cells, strongly implying that WT1 might participate in NSCLC development at least via cell motility regulation." (PMID 37667197, 2023). "Wilms’ tumor gene 1 (WT1), which was originally discovered as a protooncogene, is currently known to be expressed in many tumors, and the product of the gene—WT1 protein—is a promising tumor-associated antigen (TAA) that was ranked 1st among 75 cancer antigens and is considered as stem cell antigen." (PMID 36803483, 2023). "In the present study, undertook combination immunotherapy for RCC using an oral cancer vaccine (Bifidobacterium longum displaying WT1 tumor associated antigen (B. longum 420)) with anti-PD-1 and anti-CTLA-4 antibodies in a mouse syngeneic model of RCC to explore possible synergistic effects." (PMID 37340017, 2023). "Therefore, it is generally believed that WT1 is inactivated by point mutation or deletion so as to trigger malignant tumor." (PMID 32210734, 2020). "OC is mostly reported among these cancer types, so only taking OC into account can we find that the expression of WT1 is associated with unfavorable DSS (metaHR = 1.82, 95% CI = 1.42–2.33) and DFS/RFS/PFS (metaHR = 2.51, 95% CI = 1.81–3.48) in univariate model." (PMID 29995811, 2018). "Grade III carcinomas are associated with poorer clinical outcomes, suggesting a protective role for endothelial WT1 expression and that perturbations in vascular WT1 expression within the cancers may be crucial." (PMID 30374123, 2018). "We speculate that rs1799937 may function by altering WT1 gene expression, thus rendering cancer cells in patients with the AA allele more sensitive to anthracycline-based chemotherapy." (PMID 26573232, 2016). "Notably, perturbation of the actin cytoskeleton is essential for malignant transformation and WT1 was named as one of the proteins implicated in actin cytoskeletal changes in cancer cells." (PMID 25474318, 2014). "In the future, it could also be used as a cancer immunotherapeutic product against malignant transformation associated with WT1 over-expression." (PMID 28548069, 2014). "It is of great interest to test whether WT1 SNPs can be used as a molecular marker in other cancer types in order to improve risk and treatment stratification." (PMID 23484026, 2013).